TFAP2A-AS1 (TFAP2A antisense RNA 1)
Synonyms: MIR5689HG
Gene: Long non-coding RNA gene on chromosome 6 (10,409,340 to 10,457,192, forward strand). Ensembl gene ENSG00000229950.
Diseases named in the same sentence as TFAP2A-AS1 in open-access papers:
TFAP2A-AS1 is named in the same sentence as 1 disease in open-access papers, as found by Europe PMC text mining. Sharing a sentence is not in itself a finding about the gene and the disease. The quoted sentences say what the papers report.
cancer (1 paper, 2021). A tumor composed of atypical neoplastic, often pleomorphic cells that invade other tissues. "Utilizing the cancer genome atlas (TCGA) dataset, we found that TFAP2A antisense RNA 1 (TFAP2A-AS1) was highly expressed in almost all human cancer types, including lung squamous cell carcinoma (LUSC) and lung adenocarcinoma (LUAD)." (PMID 37305398, 2021).